DICER1 (dicer 1, ribonuclease III)
Diseases named in the same sentence as DICER1 in open-access papers (continued):
Sharing a sentence is not in itself a finding about the gene and the disease.
DICER1 syndrome (continued). "However, recent studies have indicated that patients with DICER1 syndrome have not only inherited mutations in one allele of the DICER1 gene but also acquired a somatic mutation in the second allele of the DICER1 gene." (PMID 29762508, 2018). "In addition, childhood- and adolescent-onset poorly differentiated thyroid carcinoma (PDTC) has been shown to be associated with DICER1 mutations and may herald DICER1 syndrome in some patients." (PMID 36151231, 2022). "The plethora of clinical manifestations of DICER1 syndrome is in contrast to the limited biological understanding of the function of the aberrant DICER1 protein." (PMID 40361440, 2025). "DICER1 plays an important role in normal thyroid gland development, and multiple thyroid abnormalities have been identified in DICER1 syndrome." (PMID 38254836, 2024). "Somatic DICER1 mutations give rise to thyroblastoma and childhood onset PDTC; whereas DICER1 syndrome-related manifestations include TFND, follicular adenoma with papillary architecture, PTC and FTC, pediatric thyroid nodules, as well as childhood onset PDTC." (PMID 38254836, 2024). "Mutations in DICER1 are found in differentiated thyroid carcinoma (DTC) and in multinodular goiter (MNG) at a younger age with other tumors, which characterizes DICER1 syndrome." (PMID 38330293, 2024). "Given the phenotypes identified in the patient and the presence of a VUS in DICER1, the possibility of DICER1 syndrome was revisited." (PMID 37248399, 2023). "DICER1 syndrome (OMIM 606241, 601200) is a rare autosomal dominant familial tumor predisposition disorder with a heterozygous DICER1 germline mutation." (PMID 34599283, 2022). "Despite the rarity of most DICER1 syndrome tumors, germline DICER1 PV is estimated to occur in the general population in approximately one in 10,600." (PMID 35163487, 2022). "In DICER1 syndrome, AUF1 competed with PUMILIO for binding to the DICER1 mutation allele, thereby degrading DICER1 mRNA." (PMID 36243874, 2022). "In fact, the most significant discovery regarding the molecular genetics of SLCT was the finding of underlying somatic and germline mutations in the DICER1 gene, with the occurrence of SLCT as part of an autosomal dominant disorder named DICER1 syndrome." (PMID 33922805, 2021). "She carried the DICER1 variant c.3227G>A, p.S1076N, reported in ClinVar as a VUS for DICER1 syndrome, which she inherited from her apparently healthy father." (PMID 32714280, 2020). "We found a heterozygous germline DICER1 G803E mutation in one child without a clinical diagnosis of DICER1 syndrome." (PMID 40340749, 2025). "Analogous to what occurred in this present tumor, however, a case of WDFA of the lung with coexistence of CTNNB1 and DICER1 mutations in a 16-year-old girl with a history of TFND, ovarian Sertoli-Leydig cell tumor, and familial DICER1 syndrome has been described." (PMID 40892116, 2025). "DICER1 syndrome, first characterised in 2009 and recognised in the 2022 WHO classification, is defined as an ‘autosomal dominant tumour predisposition syndrome caused by heterozygous germline pathogenic variants in DICER1’." (PMID 41104964, 2025). "Alongside thyroid surveillance, individuals with a known or suspected germline DICER1 pathogenic mutation should be enrolled in lung and ovarian surveillance for detection of early PPB and SLCT, respectively, as DICER1 syndrome increases the risk of developing these tumours." (PMID 41104964, 2025). "Mutations in DICER1 occur in both germline and somatic forms, with germline mutations being dispersed across the gene and predominantly resulting in loss of function (LOF), leading to DICER1 syndrome." (PMID 41104964, 2025). "This instance shows that the mechanism of DICER1 syndrome is not due to haploinsufficiency but rather to biallelic mutations in the DICER1 alleles." (PMID 39857323, 2025).
DICER1 syndrome (continued). "Finally, DICER1 syndrome has been added to this group due to the recognition of the involvement of DICER1 gene alterations in thyroid disease." (PMID 38254836, 2024). "The finding of DICER1 syndrome-associated neoplasms such as PPB, cystic nephroma, SLCT, TFND and DTC in children or adolescents, cERMS, gynandroblastoma, and pituitary blastoma have a high specificity for germline alterations of the DICER1 gene or DICER1 syndrome." (PMID 38254836, 2024). "Patients with DICER1 syndrome usually exhibit truncating or frameshift DICER1 alterations and may develop a plethora of tumors, including thyroid follicular nodular disease (FND) and well-differentiated thyroid carcinoma (WDTC)." (PMID 38252873, 2024). "A pertinent question emerges: Should every patient with DICER1 mutated thyroid nodules, identified through molecular workup, undergo clinical genetics evaluation to rule out DICER1 syndrome?" (PMID 38252873, 2024). "Molecular studies performed on juvenile granulosa cell tumors showed the absence of FOXL2 variant and the presence of DICER1 variants in 6–23% of the cases, sometimes associated with DICER1 syndrome." (PMID 38136408, 2023). "Importantly, diagnosis of a mesenchymal tumor with DICER1 alteration should always prompt germline testing for DICER1 syndrome." (PMID 36966138, 2023). "Long-term prospective follow-up of patients with DICER1 syndrome who remain thyroid disease-free is ongoing and may shed a new light on the pathogenesis of DICER1-related MNG." (PMID 36151231, 2022). "Developing surveillance protocols for DICER1 syndrome is challenging, not least due to uncertainty about the efficacy of surveillance for individuals with germline pathogenic DICER1 variants." (PMID 34170462, 2021). "All these findings support the assumption that DICER1 syndrome-related TC may develop in a background of MNG, via a stepwise process, involving DICER1 somatic mutations and additional molecular events, distinct from the classic pathways of TC." (PMID 33495912, 2021). "In addition, we identified pathogenic variants on which we have already reported in detail, in DICER1 in Case-10 diagnosed with DICER1 syndrome and in MSH6 in Case-7 who has a constitutional mismatch repair deficiency." (PMID 33840814, 2021). "Causality has not been proven between DICER1 loss-of-function and PitNETs other than PitB, and our patients present a phenotype quite distinct from the DICER1 syndrome." (PMID 32714280, 2020). "Given recent reports of an association of DICER1 syndrome with mesenchymal hamartoma of the liver, we specifically analyzed somatic and germline sequencing data for evidence inactivating mutation in DICER1 but found none in our cohort." (PMID 32310940, 2020). "This case demonstrates that biallelic mutations in DICER1 alleles, rather than haploinsufficiency, contribute to the mechanism of DICER1 syndrome." (PMID 29762508, 2018). "Interestingly, DICER1 mutations in thyroblastoma are somatic, not germline; thus, thyroblastoma is not currently recognized as a feature of DICER1 syndrome." (PMID 41175860, 2025). "The newly described follicular adenomas with papillary architecture have been reported to be associated with DICER1 mutations, and a subset of these were reported in patients with no previous history of chemotherapy for other DICER1 syndrome-related pathologies." (PMID 38254836, 2024). "Notably, this case was subjected to NGS testing and lacked DICER1 mutations, thus arguing against the possibility of primary metachronous pleuropulmonary blastoma in the setting of DICER1 syndrome." (PMID 32193604, 2020). "Patients with DICER1 syndrome caused by nonsense mutations similar to those already studied may benefit from using Ataluren or comparable chemicals, while no research has been conducted on DICER1 nonsense mutations using these medications." (PMID 39857323, 2025).
DICER1 syndrome (continued). "Additionally, besides the previously well described pathology in multiple organ systems related to DICER1 syndrome, other thyroid findings, like TFND, associated with follicular adenoma with papillary architecture, and DTC, should raise the concern for germline or syndromic DICER1." (PMID 38254836, 2024). "In addition, co-occurring DICER1 mutations have been similarly identified in TC patients not related to DICER1 syndrome and also in COSMIC patients where RNase IIIb domain mutations (at codons E1705 and D1709) co-occur with a second nonsense/frameshift_nonsense mutation." (PMID 37867524, 2023). "Germline information was available for 53/86 (62%) patients, of which 28/53 (53%) showed a germline provenance of the DICER1 LOF PV identified in the tumor and therefore these tumors arose in the context of DICER1 syndrome." (PMID 36966138, 2023). "Notably, it has recently been suggested that DICER1 variants may be associated with an increased risk of sporadic corticotrope adenomas, regardless of DICER1 syndrome, although no data are available to assess the pathogenic meaning of these variants." (PMID 35743266, 2022). "While no research has been conducted on DICER1 nonsense mutations utilizing drugs such as Ataluren, this drug and synonymous compounds may prove beneficial in treating patients with DICER1 syndrome stemming from nonsense mutations similar to those already tested." (PMID 29762508, 2018). "Consensus guidelines recommend the consideration of testing for DICER1 in any patient with a childhood onset MNG or DTC, especially if in combination with macrocephaly, another tumour typical of DICER1 syndrome, or a first-degree relative with an MNG/thyroid carcinoma or DICER1 syndrome features." (PMID 40361475, 2025). "We hope that our US criteria of MNG in DICER1 syndrome, when compared with a classic ultrasonographic presentation of thyroid cancer, will shed new light on which children and adults with MNG should be considered for DICER1 genetic testing." (PMID 36151231, 2022). "This assumption is indeed supported by the findings of multinodular goitre as the sole thyroid manifestation in subsets of patients with DICER1 syndrome, suggesting that DICER1 gene aberrancies not always lead to overtly malignant phenotypes." (PMID 32163919, 2020). "In an analysis of 209 DICER1‐carriers from the International PPB/DICER1 Registry and NCI DICER1 syndrome study, one case of neuroblastoma was observed, a nonsignificant excess compared with US cancer registry (SEER) data." (PMID 30672147, 2019). "In an analysis of 209 DICER1‐carriers from the International PPB/DICER1 Registry and NCI DICER1 syndrome study, a nonsignificant excess of breast cancer, prostate cancer, and melanoma was observed compared with US cancer registry (SEER) data." (PMID 30672147, 2019).
thyroid cancer (58 papers, 2014 to 2026). "Transcriptomic analyses revealed mutation-specific effects on the microenvironment, whereby DICER1 mutations activated canonical thyroid cancer progression pathways, whereas altered DGCR8 associated with immune-related changes." (PMID 41657311, 2026). "Alternatively, DICER1 mutations in the RNase IIIb domain trigger increases in RAS/ERK signaling output genes in DICER1-mutated differentiated thyroid cancers, suggesting that dysfunctional DICER1 alone drives RAS signaling pathways." (PMID 40634537, 2025). "Germline mutations in DICER1 that occur in both alleles are linked to a significantly higher risk of thyroid cancer, roughly 16 times more than the average risk." (PMID 39857323, 2025). "Individuals with DICER1 mutations have a 16- to 24-fold increased risk of developing thyroid cancer." (PMID 39860595, 2025). "Pediatric populations have been observed to exhibit poorly differentiated thyroid cancer, which is usually found in older individuals and is related to DICER1 mutations." (PMID 39857323, 2025). "By the age of 20, the cumulative incidence of FND or history of thyroidectomy is 32% in women and 13% in men carrying germline DICER1 pathogenic variants and there is a 16- to- 24-fold increased risk of thyroid cancer." (PMID 40448797, 2025). "Thyroid carcinomas are less likely to metastasize; hence, DICER1-related thyroid carcinomas are a low-risk subgroup." (PMID 39963649, 2025). "The literature points to a 16-fold increased risk of PTC or FTC in individuals with DICER1 mutations but also suggests the syndrome’s contribution to familial multinodular goiters and thyroid carcinomas is small." (PMID 39963649, 2025). "miR-135a-5p and miR-135b-5p were recently described as downregulated in DICER1 mutated pediatric thyroid cancer cases." (PMID 38252873, 2024). "Beside Dicer1 mutations, lower Dicer1 expression has been observed in numerous cancers and has been associated with aggressive features in thyroid cancer." (PMID 39409030, 2024). "Dicer1 mutations, though rare, have been found in certain thyroid cancers, including the more aggressive variants." (PMID 39409030, 2024). "In this study, we aimed to better understand the response of thyroid cancer cells to partial or total loss of Dicer1 in vitro." (PMID 39409030, 2024). "Somatic and germline DICER1 mutations in thyroid cancer arerelatively rare but have been observed in specific contexts, often associated withdistinct tumor subtypes and clinical parameters." (PMID 39601261, 2024). "Individuals carrying DICER1 mutations have a 16- to 24-fold increased risk of developing thyroid carcinoma." (PMID 38254836, 2024). "In thyroid cancer, DICER1 hotspot mutations are mutually exclusive with MAPK mutations, suggesting their ability to activate this pathway." (PMID 36896180, 2023). "In this study, we aimed to evaluate the effects of DICER1 RNase IIIb mutations on miRNA and mRNA transcriptomes of differentiated thyroid cancers." (PMID 36896180, 2023). "A literature review of 42 thyroid cancers (including cases from this study) harboring DICER1 RNase IIIb mutations reinforced the mutually exclusive nature of these alterations in thyroid cancer." (PMID 36896180, 2023). "It is worth noting that commercially available thyroid-specific miRNA panels should be used with caution in pediatric thyroid cancers where DICER1 mutations are more frequent." (PMID 36896180, 2023). "DICER1*rs3742330 increased the risk of laryngeal cancer (OR = 2.21) and conferred protection against cervical (OR = 0.73), gastric (OR = 0.70), and thyroid cancers (OR = 0.55)." (PMID 36672288, 2023). "This group reported a 16-fold increased risk of thyroid cancer, with all the cases harbouring germline and somatic pathogenic DICER1 mutations." (PMID 35255942, 2022).
thyroid cancer (continued). "Over time, numerous other manifestations have been associated with pathogenic germline variants in DICER1, including lung cysts, multinodular goiter, thyroid cancer, ovarian sex-cord stromal tumors, and cystic nephroma." (PMID 34170462, 2021). "DICER1 alterations are, hence, driver mutations in at least a proportion of adolescent-onset benign and malignant thyroid tumors." (PMID 35008368, 2021). "Thyroid cancer dedifferentiation is an unusual observation among young patients and is poorly understood, although a recent correlation to DICER1 gene mutations has been proposed." (PMID 34389035, 2021). "The analysis of the gender-related risk of thyroid cancer is difficult for the DICER1 gene, coding for an endoribonuclease." (PMID 34884794, 2021). "Another study starting from search for DICER1 variants in the population found the same number of thyroid cancers in males and females (one for each sex) among carriers of pathogenic variants." (PMID 34884794, 2021). "To date, approximately 30 patients with (suspected) DICER1-associated thyroid cancer have been reported." (PMID 34170462, 2021). "This study was able to identify less common (pineoblastoma) and more common (thyroid carcinomas) DICER1-associated neoplasms as well as a potentially novel DICER1-associated neoplasm (renal cell carcinoma) that merits additional follow-up." (PMID 33630087, 2021). "Enforced evidence of DICER1 mutation with familial thyroid cancer was also shown in a study with six individuals of the same family harboring DICER1 mutation (c.5441C>T, p.S1814L) and multiple cases of differentiated thyroid cancer and MNG." (PMID 33218058, 2020). "In recent years there have been reports of DICER1 gene mutations in several endocrine malignancies, including thyroid cancer." (PMID 32163919, 2020). "In FTC cell lines, we observed reduced expression levels of the thyroid-cancer associated miRNA miR-34a-5p upon DICER1 or GABPA depletion, suggesting that components of the miRNA machinery are affected by the general DICER1 down-regulation seen in FTCs." (PMID 32163919, 2020). "Taken together, these data suggest that, similar to other tumor types, low DICER1 levels in thyroid cancer are associated with advanced tumor stage and poor clinical outcome." (PMID 30967628, 2019). "Our analysis of The Cancer Genome Atlas revealed a general decrease in DICER1 expression in thyroid cancer that was associated with a worse clinical outcome." (PMID 30967628, 2019). "Of the 32 types of tumors sequenced in the TCGA project with available DICER1 germline data, only one (thyroid carcinoma) has genetic and epidemiologic evidence of an association with pathogenic germline DICER1 variation." (PMID 30672147, 2019). "Moreover, DICER1 andDGCR8 mutations have also been reported in rare subsets offollicular cell-derived thyroid carcinomas." (PMID 39601261, 2024). "We next sought to determine whether this unique miRNA signature of tumors with RNase IIIb mutations could be used to identify thyroid cancers harboring DICER1 hotspot mutations." (PMID 36896180, 2023). "As a result, there has been considerable speculation on a possible link between chemotherapeutic agents and an increased risk of differentiated thyroid cancer due to somatic DICER1 mutations." (PMID 35255942, 2022). "Several poorly differentiated thyroid cancers harbored DICER1 variants." (PMID 35679040, 2022).